PRPSAP1 (phosphoribosyl pyrophosphate synthetase associated protein 1)
Description:
Seems to play a negative regulatory role in 5-phosphoribose 1-diphosphate synthesis.
Synonyms: PAP39
Tractability: Small molecule: it has a binding pocket of medium quality. PROTAC: ubiquitination databases record sites on it; its protein half-life has been measured.
Gene: Protein-coding gene on chromosome 17 (76,309,478 to 76,384,521, reverse strand). Ensembl gene ENSG00000161542.
Subcellular location (Human Protein Atlas): Cytosol
Gene Ontology:
Molecular function: identical protein binding; protein binding; enzyme inhibitor activity; enzyme regulator activity; magnesium ion binding
Biological process: 5-phosphoribose 1-diphosphate biosynthetic process; nucleobase-containing compound metabolic process; purine nucleotide biosynthetic process; nucleotide biosynthetic process
Cellular component: cytoplasm
Genetic constraint (gnomAD): Loss-of-function variants: 22 observed, 28.77 expected, observed/expected ratio (o/e) 0.76, 90% interval 0.55 to 1.09. The upper end of that interval is the gene's LOEUF score, 1.09, which puts it in group 4 of 6, group 1 being the genes least tolerant of losing a copy. Missense variants: 373 observed, 445.85 expected, observed/expected ratio (o/e) 0.84, 90% interval 0.77 to 0.91. Synonymous variants: 195 observed, 170.57 expected, observed/expected ratio (o/e) 1.14, 90% interval 1.02 to 1.29.
Homologues: Orthologues: chimpanzee PRPSAP1 (99% identical), macaque PRPSAP1 (99% identical), pig PRPSAP1 (98% identical), mouse Prpsap1 (97% identical), guinea pig PRPSAP1 (97% identical), rat Prpsap1 (97% identical), dog PRPSAP1 (88% identical), rabbit PRPSAP1 (85% identical), tropical clawed frog prpsap1 (75% identical), Drosophila melanogaster CG2246 (60% identical), Caenorhabditis elegans W04G3.5 (53% identical), zebrafish prpsap1 (40% identical). Paralogues in human: PRPSAP2 (73% identical), PRPS2 (41% identical), PRPS1 (40% identical), PRPS1L1 (39% identical).
Diseases named in the same sentence as PRPSAP1 in open-access papers:
PRPSAP1 is named in the same sentence as 6 diseases in open-access papers, as found by Europe PMC text mining. Sharing a sentence is not in itself a finding about the gene and the disease. The quoted sentences say what the papers report.
lymphoma (2 papers, 2025). A malignant (clonal) proliferation of B- lymphocytes or T- lymphocytes which involves the lymph nodes, bone marrow and/or extranodal sites. "We first confirmed that the PRPS isozymes co-assemble, together with the PRPS associated proteins (PRPSAP1, PRPSAP2), to form a complex in Myc-dependent lymphoma cells." (PMID 40446642, 2025).
glioma (1 paper, 2022). A benign or malignant brain and spinal cord tumor that arises from glial cells (astrocytes, oligodendrocytes, ependymal cells). "Furthermore, the expression of PRPS1, PRPS2, PRPSAP1 (PAP39) and PRPSAP2 (PAP41) genes in U87 glioma cells is not inhibited by ERN1 (EC 2.7.11, endoribonuclease activity of endoplasmic reticulum to nuclei-1)." (PMID 35741038, 2022).
Insulin resistance (1 paper, 2012). Increased resistance towards insulin, that is, diminished effectiveness of insulin in reducing blood glucose levels. "The results of differentially expressed genes associated with insulin resistance indicate that PRPSAP1 gene is associated with percentage of body fat." (PMID 23241142, 2012).
PRPSAP1 also shares sentences with these, for which no sentence is quoted: tumor (2 papers); neuroblastoma (1); prostate carcinoma (1).